CRYGEP (crystallin gamma E, pseudogene)
Synonyms: G2; formerly CRYG5; CCL; CRYGEP1
Gene: Transcribed unitary pseudogene on chromosome 2 (208,108,233 to 208,112,511, reverse strand). Ensembl gene ENSG00000229150.
Diseases named in the same sentence as CRYGEP in open-access papers:
CRYGEP is named in the same sentence as 4 diseases in open-access papers, as found by Europe PMC text mining. Sharing a sentence is not in itself a finding about the gene and the disease.
CRYGEP shares sentences with these, for which no sentence is quoted: asthma (1 paper); atherosclerosis (1); psoriasis (1); systemic sclerosis (1).